LEP (leptin)
Diseases named in the same sentence as LEP in open-access papers (continued):
Sharing a sentence is not in itself a finding about the gene and the disease.
Insulin resistance (continued). "One adipokine, leptin, is typically positively correlated with fat mass, however in the ZDF model of extreme insulin resistance and a defective leptin receptor, this correlation is lost, a finding confirmed in the present experiment (r=0.0703, p=0.65)." (PMID 23146593, 2012). "Leptin administration in replacement doses in HIV-positive patients with partial lipoatrophy improved glycemia, dyslipidemia, and insulin resistance." (PMID 21760816, 2011). "The molecular pathways that link inflammation and insulin resistance include a variety of cytokines and adipocytokines such as TNF-α, IL-6, MCP-1, leptin, and adiponectin." (PMID 21403905, 2010). "Our primary outcomes are serum concentrations of leptin, adiponectin, TNF-α, C-reactive protein (CRP), IL-6 and insulin resistance." (PMID 20550712, 2010). "Decreases in BMI, body weight, fat mass, fat free mass, triglycerides, insulin resistance (HOMA-IR), and leptin were observed following RYGB." (PMID 19936240, 2009). "Serum cortisol levels are the best predictor for inflammatory insulin resistance followed by IL6, leptin and adiponectin." (PMID 19087258, 2008). "Testing the relevance of each parameter to predict insulin resistance we found best performance for serum cortisol followed by serum IL6, leptin and adiponectin." (PMID 19087258, 2008). "Model assessment identified cortisol as the best predictor of insulin resistance, followed by IL6, leptin and adiponectin." (PMID 19087258, 2008). "Leptin levels are, however, elevated in MASLD and advocate for inflammation and insulin resistance." (PMID 41220583, 2025). "Leptin, an adipokine secreted predominantly by white adipose tissue, is often elevated in obese individuals with PCOS and has been positively correlated with insulin resistance and hyperinsulinemia." (PMID 40792318, 2025). "Leptin resistance and impaired LEPR signaling contribute to the development of hepatic insulin resistance and are associated with several conditions, such as nonalcoholic fatty liver disease (NAFLD)." (PMID 39823117, 2025). "Anthropometric parameters, body composition, body fat percentage, surrogate markers of insulin sensitivity (Homeostasis model assessment of insulin resistance index—HOMA-IR and ISI Matsuda), and circulating levels of leptin and adiponectin were measured in all participants." (PMID 40075777, 2025). "IL-4 influences lipid metabolism via STAT6, promoting adipogenesis, lipolysis, and reducing leptin levels, thereby improving insulin resistance or inducing white adipose browning in the absence of leptin." (PMID 41007770, 2025). "Metabolically unhealthy COPD patients have higher levels of leptin, lower levels of adiponectin, and increased insulin resistance, compared with patients without metabolic syndrome." (PMID 40868072, 2025). "In an apparently healthy overweight or obese population, our study offers early evidence of a correlation between circulating leptin levels and hepatic fibrosis, independent of age, gender, and insulin resistance." (PMID 40507178, 2025). "Leptin levels were comparable across tertiles in the total population, possibly because women with the highest LIS gained less gestational weight, thereby lowering insulin resistance and leptin resistance." (PMID 41374008, 2025). "Targeted gene deletions in mouse models highlight their unique functions - leptin knockouts develop severe obesity with decreased energy expenditure, while mice lacking adiponectin exhibit profound insulin resistance." (PMID 40630101, 2025). "This is in line with studies that view leptin primarily as a surrogate of fat mass rather than a direct mediator of insulin resistance or diabetes." (PMID 41523554, 2025). "Furthermore, we observed a strong association between placenta‐derived C19MC miRNAs and placental weight and UCP insulin neonatal and insulin resistance, in addition to between pregnancy‐specific C14MC miRNAs with maternal BMI and UCP leptin." (PMID 40013652, 2025).
Insulin resistance (continued). "In contrast to RBCD, AI was associated with T2D (p < 0.001), BMI (p < 0.001), insulin resistance (HOMA-IR, p = 0.033), leptin (p < 0.001), C-peptide levels (p = 0.009), but not vascular complications (p = 0.156)." (PMID 41408588, 2025). "Additionally, AGRP significantly decreased homeostatic assessment of insulin resistance (HOMA-IR) scores, as well as leptin and LTB4, markers involved in immunity and inflammation in HFD mice." (PMID 40557240, 2025). "The brain then fails to respond to the appetite-suppressing effects of leptin and the result is hyperphagia (overeating), weight gain, and exacerbated insulin resistance." (PMID 40722840, 2025). "Adipokines such as leptin and TNF-α, secreted from adipose tissue, may further aggravate insulin resistance and impair β-cell function." (PMID 41036138, 2025). "Additionally, women with post-GDM T2D had increased insulin-resistance index HOMA-IR, circulating lipids, leptin, and blood pressure." (PMID 39589852, 2024). "It has been proposed that, in adolescents, leptin and LAR are associated with high insulin resistance independent of potential confounders (age, sex, pubertal stage, adherence to the Mediterranean diet, cardiorespiratory fitness, and body fat percentage)." (PMID 38289144, 2024). "Unfortunately, we have not found correlations with other insulin-resistance biochemical markers such as leptin, microalbuminuria or C-reactive protein." (PMID 38734755, 2024). "Background and Objectives: In this study, the effects of an eight-week exercise and nutrition program on blood lipids, glucose, insulin, insulin resistance (HOMA-IR), leptin, ghrelin, irisin, malondialdehyde (MDA), and Growth Differentiation Factor 15 (GDF15) in overweight women were investigated." (PMID 39768899, 2024). "In recent years, researchers have found that SOCS3 is involved in the AMPK signaling pathway, insulin resistance, adipocytokine signaling pathway, and JAK/STAT pathway, is activated/triggered by leptin signals, and plays important roles in lipid metabolism processes." (PMID 38415055, 2024). "At the age of 6 months, male HDAC5-KO mice further showed significantly elevated HOMA-IR levels, indicating insulin resistance, as well as elevated plasma leptin, cholesterol and non-esterified free fatty acids (NEFA) levels." (PMID 39304061, 2024). "It seems that factors like BMI and fatness, related to leptin in younger children, do not fully explain this insulin resistance that occurs during the Tanner stages of puberty." (PMID 39685744, 2024). "This includes insulin resistance, glucose intolerance, hepatic steatosis, very low adiponectin and leptin levels and hyperphagia, although not the hypertriglyceridemia observed in CGL2 patients." (PMID 38745956, 2024). "Lipodystrophy is characterized by a partial or total absence of adipose tissue and very low levels of leptin, leading to severe metabolic derangements, including marked insulin resistance, type 2 diabetes, and cardiovascular disease (CVD)." (PMID 38397015, 2024). "It is possible that, in our case, coupled also with the increase in leptin, insulin resistance did not overcome the physiological threshold, and the change in metabolic fuels related to the placenta favored the decrease in TGs we observed." (PMID 39479521, 2024). "Instead, leptin induces SOCS3 expression in keratinocytes, resulting in the inhibition of leptin signaling through negative feedback and insulin resistance, which interfered with their differentiation." (PMID 38975347, 2024). "In line with our results, it has been demonstrated that miR-1 could reduce mice insulin resistance through AMPK activation, which is an important mediator of leptin effects." (PMID 39796132, 2024). "Additionally, only in boys, both plasma leptin and LAR also showed a significant and similar capacity to identify insulin resistance from sensitivity." (PMID 38289144, 2024).
Insulin resistance (continued). "Hospitalised COVID-19 patients with hyperglycemia also presented a higher prevalence of insulin resistance when compared to ARDS (acute respiratory distress syndrome)-positive and ARDS-negative controls, due to changes in adipokine levels (adiponectin and leptin), instead of beta-cell function." (PMID 38548777, 2024). "Furthermore, leptin can also promote lipolysis and increase serum FFA, thereby exacerbating insulin resistance." (PMID 40302954, 2024). "Hyperglycemia, insulin resistance, elevated insulin, and insulin-like growth factor-1 (IGF-1) levels, inflammatory cytokines, dyslipidemia, increased leptin, and decreased adiponectin have all been attributed to the increased risk of cancer in patients with diabetes." (PMID 39020360, 2024). "In fact, the opposing action of insulin and leptin can explain why animals with HFHSD did not develop polyphagia despite the potential development of central insulin resistance." (PMID 37929025, 2023). "By raising adiponectin levels and lowering leptin, CUR can reduce insulin resistance." (PMID 36932309, 2023). "Additionally, this group displayed higher levels of leptin compared with the control (NF) and leptin-treated animals (HFD-Lep), along with signs of insulin resistance, such as increased fasting glycemia and insulinemia and increased HOMA-IR index." (PMID 38203399, 2023). "Third, some serum markers including serum insulin and leptin level, hepatic and peripheral insulin resistance, were not measured in the current study." (PMID 36658285, 2023). "In particular, diet supplementation with HSH supplement ameliorated insulin resistance in high-fat-induced obese mice, while diet supplementation with HMB and HMH nutritional supplements eliminated leptin expression in the adipose tissue independently of abdominal fat accumulation in obese mice." (PMID 37367668, 2023). "Also, the remediation of obese rats with ZnONPs led to a significant decrease in body mass index (BMI), body weight gain, leptin, cholesterol, triglycerides, LDL (Low-density lipoprotein), glucose, and insulin resistance index (HOMA-IR)." (PMID 37749096, 2023). "In this context, an adipocyte-α derived factor, such as TNF-, leptin, FFA, and resistin, could be the mediator of oxidative stress-induced insulin resistance in the pre-diabetic condition." (PMID 37175603, 2023). "Although our study did not consider the measurement of insulin resistance, leptin, and SHBG (to calculate free T), wc, BMI, and estradiol levels were elevated, supporting this pathophysiologic pathway." (PMID 36282472, 2023). "To further evaluate the effect of central leptin on hepatic glucose flux in the presence of altered nutrition sensing in the periphery for PCOS rats, we constructed an acute insulin resistance model induced by peripheral lipid infusion in ND-fed PCOS rats during the clamps." (PMID 37660067, 2023). "In summary, we must find the intermediate steps between absent or insufficient leptin action and insulin resistance." (PMID 38260129, 2023). "Furthermore, leptin and CRP increase insulin resistance whereas adiponectin improves insulin sensitivity; primary features of GDM." (PMID 36520252, 2023). "Other pharmacodynamic targets, such as brain-derived neurotrophic factor (BDNF) and leptin (LEP), may also be involved in risperidone-induced insulin resistance." (PMID 38375208, 2023). "This is in line with the lack of insulin resistance observed in animals treated with leptin in comparison to control, non-treated MONW rats." (PMID 35684076, 2022). "Analogically to insulin resistance, despite elevated blood leptin, it does not mediate its effects, in general due to the impairment either of leptin transport into the brain, or the central response." (PMID 36131679, 2022). "Yet in this study leptin replacement at doses that reverse insulin resistance and systemic inflammation does not affect urine oxalate excretion in food‐restricted ob/ob mice." (PMID 35851836, 2022).
Insulin resistance (continued). "Serum thyroid-stimulating hormone (TSH), free triiodothyronine (fT3), free thyroxine (fT4), fasting blood glucose, fasting insulin, homeostatic model assessment method of insulin resistance (HOMA-IR), leptin, and adiponectin levels were estimated in all participants." (PMID 35501770, 2022). "The study showed no changes in leptin and adiponectin, despite a significant decrease in adiposity, plasma lipids, and insulin resistance in weight-excess individuals." (PMID 35741374, 2022). "Most authors have observed that, from the first trimester to the early third trimester, adiponectin concentrations are decreased and leptin concentrations are increased in women with GDM, and correlate with data of insulin resistance, altered lipid metabolism, and excess body weight." (PMID 35682958, 2022). "In our study, reduction of insulin resistance of ob/ob mice by pioglitazone treatment (or leptin replacement) does not lower urine oxalate excretion." (PMID 35851836, 2022). "Insulin resistance in obese patients can be explained due to the inflammatory response with alteration of substances that act systemically, participating in several metabolic processes, such as leptin, adiponectin, and TNF-α, which play a fundamental role in insulin resistance." (PMID 35703718, 2022). "Insulin resistance is partly attributed to the dysregulation of adipocytes, which produce and secrete several cytokines called adipocytokines, e.g., tumor necrosis factor-α(TNF-α), adiponectin, leptin, and plasminogen activator inhibitor-1 (PAI-1)." (PMID 35010830, 2022). "In addition, Metabolic dysfunction, including inflammation, insulin resistance, hypothalamic–pituitary–adrenal (HPA) axis dysregulation and central leptin resistance, have emerged as key risks to depression and anxiety development." (PMID 35692399, 2022). "Novel findings from this study include the associations of non-freeway but not freeway NRAP with leptin levels and with the ratio of leptin to adiponectin, which are functional measures of AT inflammation and insulin resistance, in blood or AT." (PMID 35305663, 2022). "Therefore, we planned to explore those effects by measuring the homeostasis model assessment ratio of insulin resistance (HOMA-IR) and plasma level of leptin and adiponectin." (PMID 35350513, 2022). "We may conclude that increased leptin concentrations in CKD male patients may lead to decreased muscle mass by elevating inflammatory status and insulin resistance." (PMID 36675692, 2022). "They found apnoeic males showed higher hsCRP, IL-6, leptin, and insulin resistance than controls, while no significant influence can be observed in these biomarkers after CPAP treatment." (PMID 36105285, 2022). "In addition, chemerin levels correlated positively with gestational BMI, Homeostatic Model Assessment-Insulin Resistance (HOMA-IR), and glucose, and leptin levels with HOMA-IR, and insulin." (PMID 35682958, 2022). "In women, plasma CNTF showed a moderate correlation with WHR; notably, there was a strong correlation with BMI, the insulin resistance indices fasting insulin and HOMA index and the inflammatory markers hsCRP and IL-6, as well as a very strong correlation with leptin." (PMID 35585213, 2022). "Excessive fat tissue does not merely elevate plasma leptin levels but relates to insulin resistance, which is a crucial feature of metabolic disorders." (PMID 36143007, 2022). "As there is substantial weight gain and increased leptin release through the placenta in pregnancy, regardless of insulin resistance, leptin levels in pregnancy are debatable." (PMID 36128550, 2022). "Animal models lacking leptin or the leptin receptor (ob/ob and db/db mice, respectively) show weight gain, hyperinsulinemia, insulin resistance, and impaired glucose homeostasis." (PMID 35628332, 2022).
Insulin resistance (continued). "Second, a novelty of our study was in discovering the strong relationship between leptin and insulin resistance in a community-dwelling population; there is no similar research that investigates this topic in the middle-aged and older populations in Taiwan." (PMID 36143007, 2022). "Additionally, we computed the following: leptin-adiponectin ratio (LAR), Homeostatic Model Assessment for Insulin Resistance (HOMA-IR) and Adipose Tissue Insulin Resistance (AT-IR) indices." (PMID 35279219, 2022). "High %BF in this population was associated with higher leptin and higher CRP concentrations, which have been closely linked to insulin resistance, a known risk factor for noncommunicable diseases." (PMID 33680494, 2021). "In addition, the placenta produces TNF-α and leptin, which are highly relevant in GDM pathogenesis since they induce insulin resistance in peripheric tissues and have been proposed as molecules involved in insulin resistance during pregnancy." (PMID 34769262, 2021). "In obesity, leptin and insulin resistance are accompanied by increased levels of GM3 synthase in animal and human studies; the genetic deletion of ST3GAL5 has rescued insulin resistance in mice fed with a high-fat diet." (PMID 34944404, 2021). "GHCA was inversely associated (Spearman’s correlation, FDR-corrected P < 0.05) with BMI, waist circumference, body fat percentage, insulin resistance (HOMA-IR), fasting circulating levels of triglycerides and leptin (P = 5.3e-4, 3.1e-3, 6.7e-5, 3.8e-3, 1.3e-2, 5.1e-5, respectively, FDR-corrected)." (PMID 34168163, 2021). "A major function of leptin is to regulate consumed energy and received energy, and prevent the accumulation of fats in non-adipose tissues such as the liver, and in hepatic insulin resistance indirectly plays a role in preventing liver fibrosis." (PMID 33793621, 2021). "Although leptin levels were not different among the groups, the leptin/adiponectin ratio, which has been shown to be a predictor of metabolic syndrome and insulin resistance, was significantly increased in the TBI group and trending upward in the ABM group." (PMID 34554929, 2021). "We previously demonstrated that the plasma PAI‐1 levels, but not the leptin levels, of obese Japanese children were also significantly correlated with insulin resistance indexes, such as the immunoreactive insulin (IRI), HOMA‐R and QUICKI values." (PMID 33532616, 2021). "Here, we showed that MSI-1436 significantly reduces secretion of leptin by EMS derived adipocytes, which may protect against development of insulin resistance and restore physiological adipocyte secretome." (PMID 33536069, 2021). "Four weeks of supplementation with TAN and HMF resulted in intermediate levels of blood serum glucose, leptin, resistin, and insulin resistance compared with the healthy control and the nonsupplemented HFD groups." (PMID 33841818, 2021). "This notion was further supported by who showed that inactivation of SOCS3 in LepR-expressing cells protects mice against diet-induced insulin resistance, indicating that SOCS3 is a critical downstream signaling mediator of leptin to orchestrate glycemic control." (PMID 33935782, 2021). "Adiponectin levels has negative correlation, while leptin and resistin levels has positive correlation with insulin resistance in diabetic individuals." (PMID 33641315, 2021). "Moreover, adipocytes secrete mediators of insulin resistance, namely, TNF-β, leptin, adiponectin, and resistin." (PMID 34595217, 2021). "Although the ovariectomized rats of the present study exhibited higher blood levels of leptin, no signs of insulin resistance were observed." (PMID 33420094, 2021). "Interestingly, the male antibiotic groups (ABT, ABT + PRE) had increased leptin levels compared to CTR at the end of the study, however, fasting insulin levels as well as insulin resistance was strictly increased in the ABT group." (PMID 33445530, 2021).